ICAM1 (intercellular adhesion molecule 1)
Diseases named in the same sentence as ICAM1 in open-access papers (continued):
Sharing a sentence is not in itself a finding about the gene and the disease.
tumor (continued). "Challenging this, in the cohort of triple negative patients approximately 60% of the samples had ICAM1 positive tumor cells." (PMID 30082828, 2018). "In a first phase (elimination phase), the stimulated immune system produced many costimulating cytokines (TNFα, IL1, IFNα, TLR, ICAM1, IL2, IL12, IFNγ,) and less inhibitors (IL10, IL4, IL13, PD1/PD-L1, prostaglandins, LAG-3, TGFβ) resulting in efficient tumor cell killing." (PMID 29492219, 2018). "Therefore, we examined the expression of ICAM-1 and VCAM-1, the two well-established CAMs with a key role in tumor metastasis." (PMID 28903329, 2017). "Anti-tumor T cell potency in vitro was directly proportional to CAR affinity and ICAM-1 density." (PMID 29085043, 2017). "Although the expression of ICAM-1 and VCAM-1 were significantly increased when endothelial cells were treated with PT, we demonstrated that this effect is not linked to the PT-evoked tumor cell adhesion." (PMID 29100413, 2017). "According to our data, the ligands most upregulated by IFNγ were PD-L1, ICAM-1, and MHC-class I; therefore, we determined whether changes in their expression correlated to changes in tumor lysis after IFNγ treatment." (PMID 28428785, 2017). "In the next step, we conducted the immunohistochemical (IHC) staining for tumor samples to detect the expressions of MYLIP and cell adhesion molecules (E-Cadherin, ICAM-1 and Integrin β1) and let the pathologists to determine their relative IHC scores in miR-19b agomir and agomir control groups." (PMID 28969074, 2017). "Using organotypic cell cultures submitted to three-dimensional collagen-rich contraction assays after RNAi-mediated knock down of LIF-responsive genes, we show that membrane-bound ICAM-1 triggers tumorigenic ECM remodeling in CAF and in fibroblasts undergoing activation by tumor cells." (PMID 27901489, 2017). "We consider how LFA-1 mediates the interaction of leukocytes with tumors and the role of ICAM-1 in tumor dynamics, which can be independent of its interaction with LFA-1." (PMID 29099772, 2017). "Indeed, ICAM-1 is inducible in CCC cells under starvation of both O2 and long chain fatty acids (LCFAs), thereby facilitating cell survival and tumor growth." (PMID 28417928, 2017). "We suspect that cytokine-induced ICAM-1 overexpression is a reason for the onset of toxicity mediated by the high affinity CAR T cells, as demonstrated by the lack of apparent toxicity following TM CAR T treatment in non-tumor bearing animals." (PMID 29085043, 2017). "As the transcription of ICAM1 and MCP1 were inhibited with W10, we detected whether W10 inhibited the migration of tumour cells with scratch testing." (PMID 28095903, 2017). "Interestingly, the PT-induced upregulation of ICAM-1, VCAM-1 and CXCL12 were dispensable for the PT-evoked tumor cell adhesion." (PMID 29100413, 2017). "Later, it was reported that murine LAK cells kill more efficiently mouse tumor cells transfected with human ICAM-1 than parental non-transfected cells." (PMID 29312326, 2017). "Notably, activation of FBXO4 deregulated EMT and tumor progression, including processes such as cell migration and invasion, and FBXO4 regulated ICAM-1 stability via the ERK pathway." (PMID 29137327, 2017). "On the other hand, pomegranate juice and the combination upregulated genes involved in cell adhesion, in particular E-cadherin in PC3 cells, claudin 1 (CLDN1) in MCF7 cells, and intercellular adhesion molecule 1 (ICAM1) and myristoylated alanine-rich protein kinase C (MARCKS) in both tumor models." (PMID 26180600, 2015). "Furthermore, stimulation of CD137 on tumor endothelial cells via an agonistic antibody upregulates ICAM1, VCAM1, and E-selectin and thereby enhances T-cell recruitment into tumor tissue." (PMID 26500646, 2015). "Previous studies underscore the pivotal role of ICAM-1 in the rejection of immunogenic tumors but not for clearance of systemic infections, suggesting their particular role in anti-tumor immunity." (PMID 26068788, 2015).
tumor (continued). "Anti-E-selectin antibody was able to significantly block tumor cell binding, whereas neutralization of ICAM-1 and VCAM-1 did not significantly affect tumor cell binding." (PMID 26509633, 2015). "However, treatment of cells with the combination of mL4-3 and L1-7(N) modulated tumor-cell phenotype, increasing the surface expression (either percentage or MFI) of CEA, MUC-1, ICAM-1, Fas, Trail-R1, Trail-R2, and calreticulin." (PMID 26579226, 2015). "It is likely, however, that upregulation of ICAM-1 is not the only mechanism by which blockade of Ang1 and Ang2 increased the sensitivity of tumor cells to CTL mediated lysis." (PMID 26579226, 2015). "Do ICAM1 and CD44 share common signaling networks to maintain tumor stemness?" (PMID 26571024, 2015). "After this initial interaction, firm adhesion takes place, mediated by several cell adhesion molecules belonging to the integrin family as well as the Intercellular Adhesion Molecule-1 (ICAM-1) and Vascular Cell Adhesion Molecule-1 (VCAM-1) from the immunoglobulin family, leading to tumor invasion." (PMID 24857933, 2014). "In our work, we found that NF-κB induced the expression of CXCL1, ICAM1 and TNFAIP3 after doxorubicin treatment only in a subset of tumors, suggesting that differences in responses may exist among tumor subtypes." (PMID 24344116, 2014). "Indeed, the gene TNFSF11 contributes to tumor metastasis acting through MEK/ERK, which in turn activates NFKB, resulting in the activation of ICAM1." (PMID 24489837, 2014). "This firm adhesion constructed by CD103-E-cadherin interaction is crucial for CTLs to kill tumor cells especially when tumors do not express ICAM-1." (PMID 25390652, 2014). "There were slightly stronger expression of TNC and ICAM1 in the seeding-positive tumors, but the immunopositive areas were restricted to tumor stroma rather than tumor cell clusters where the majority of ID3-immunoreactivity was found." (PMID 23768125, 2013). "Continuous section slides were stained for ICAM-1, VCAM-1 and CIK cells respectively to figure out the spacial relationship between CIK cells infiltration and the endothelial cell adhesion molecules within the tumor." (PMID 23799045, 2013). "Although 10 mg/kg artesunate did not significantly inhibit A549 xenograft tumor proliferation (P > 0.05), artesunate decreased the ICAM-1 and MMP-9 protein levels in the mouse model (P < 0.05)." (PMID 24229621, 2013). "In addition, up-regulation of ICAM-1 expression is correlated with the cancer stage and distant metastasis, suggesting that ICAM-1 plays a central role in tumor progression and metastasis." (PMID 23098564, 2012). "The changes mediated by ATRA inhibit cell adhesion and trans-endothelial migration, pinpointing a unique regulatory role of specific glycosyltransferases in the biological behaviors of tumor cells and highlighting the novel ATRA function of modulating the N-glycan composition of ICAM-1." (PMID 23300837, 2012). "Reduced expression of ICAM-1, MMP-9 and VEGF might be responsible for diminished invasion of tumor cells in cryptopleurine treatment." (PMID 22768286, 2012). "In addition, ATRA has been shown to modify the immunogenicity of tumor cells both in vitro and in vivo through differential regulation of MHC class I and intercellular adhesion molecule-1 (ICAM-1)." (PMID 22091432, 2011). "Furthermore, MA decreased the expression levels of NF-κB-regulated genes, including genes involved in tumor cell proliferation (Cyclin D1, COX-2 and c-Myc), apoptosis (Survivin, Bcl-2, Bcl-xl, XIAP, IAP-1), invasion (MMP-9 and ICAM-1), and angiogenesis (VEGF)." (PMID 20367887, 2010). "It is known that ICAM-1 can be aberrantly expressed in CRC and suppress cancer progression via activation of the host immune surveillance system and prevention of cells from detaching from the primary tumor mass and thus attenuate or eliminate metastasis." (PMID 19822019, 2009).
tumor (continued). "Additionally, we found intercellular adhesion molecule 1 (ICAM1), a cell-adhesion molecule also binding to integrin beta-2 and promoting metastasis due to tumor cell adhesion to endothelium overexpressed in AC." (PMID 18992152, 2008). "The vaccination regimen consisted of vaccinia virus expressing tumor antigens carcinoembryonic antigen (CEA) and mucin-1 (MUC-1) with three costimulatory molecules B7.1, ICAM-1 and LFA-3 (TRICOM) (PANVAC-V) and fowlpox virus expressing the same antigens and costimulatory molecules (PANVAC-F)." (PMID 18039393, 2007). "In this model we found that nonstimulated MEC and tumour cells did express E-Selectin, ICAM-1, and VCAM-1." (PMID 17088916, 2006). "Both found significant increased ICAM-1 expression after preincubation with the ROS, although a relation with tumour adhesion was not investigated." (PMID 17088916, 2006). "Using conditioned media (CM) from seven ICAM-1-positive or -negative neoplastic cells, we demonstrate that tumour-derived interleukin 1alpha (IL-1alpha) significantly (P < 0.05) up-regulates the release of sICAM-1 by human umbilical vein endothelial cells." (PMID 9374368, 1997). "Additionally, intercellular adhesion molecule 1 (ICAM-1) has been shown to be essential for T-cell priming, as its expression as a co-stimulatory molecule is critical for the immunogenic properties of DEX in the anti-tumor immune response." (PMID 40503230, 2025). "Furthermore, multiplex IHC revealed the distinct co-localisation patterns of ICAM-1 with CD31, CD8, and CD103 in PAK1KO and PAK4KO tumours, indicating enhanced vascular activation and increased activation of immune cells, such as cytotoxic CD8+ T-cells and CD103+ dendritic cells." (PMID 40943273, 2025). "Moreover, expression of ICAM-1 has been reported in OSCC cells, and thus CD18 could also be essential for tumor-neutrophil crosstalk." (PMID 40549016, 2025). "TGF-β further polarizes TANs to the pro-tumor N2 phenotype, whereas blocking TGF-βpromotes the accumulation of N1-TANs and upregulates chemotaxis/adherence and cytotoxic-related programs (such as CXCL1/2/5, ICAM-1), synergizing with CD8+ T cells to suppress tumor growth." (PMID 41473772, 2025). "Furthermore, we found that EVs are imported by endothelial cells in vivo, independent of tumor HuR status, and that WT EV import leads to decreased intercellular adhesion molecule 1 (ICAM-1) surface expression in endothelial cells." (PMID 40814996, 2025). "The absence of ICAM-1 may also contribute to the resistance of cancer cells by precluding specific immune cells to interact with the tumor tissue." (PMID 40071851, 2025). "Additionally, the movement of T-cells from blood vessels to the tumor site is hindered by the downregulation of extravasation mediators, including vascular cell adhesion molecule-1 (VCAM-1) and intercellular adhesion molecule-1 (ICAM-1)." (PMID 41019052, 2025). "Researchers found that TNBC cells release ICAM1-enriched small EVs and the binding of ICAM1 to its receptor is necessary for the suppressive effect on CD8 + T cell activity, creating an immunosuppressive TME that may contribute to TNBC tumor growth and bone metastasis." (PMID 40691627, 2025). "In tumor samples, ICAM-1 levels presented a negative correlation with SCS." (PMID 40652770, 2025). "Additionally, cytokine-induced proteins, including intercellular adhesion molecule-1 (ICAM-1) are emerging as indicators of tumor progression and immune modulation, although not all are directly linked to EGFR pathways." (PMID 40881677, 2025). "Furthermore, tumor-derived exosomal CMTM4 induces M2 macrophage polarization and immune suppression via the NF-B pathway and ICAM1 upregulation, promoting metastasis and attenuating anti-PD-1 sensitivity; its inhibition with Eltrombopag can enhance immunotherapy." (PMID 41280929, 2025).
tumor (continued). "Additionally, the whole tissue section staining confirms this pattern, showing ICAM1 is predominantly expressed in tumor cell regions while being low or absent in surrounding stromal and non-cancerous areas." (PMID 39971940, 2025). "The overall median CD3+/ICAM-1+ T cell density was 5.0 cells/mm2 (range 0.1–144.9 cells/mm2), with non-statistically significant higher numbers of CD3+/ICAM-1+ T cells in the stroma (4.8 cells/mm2, range 0.1–373.3 cells/mm2) than in the tumour compartment (1.7 cells/mm2, range 0.0–22.1 cells/mm2)." (PMID 39792888, 2025). "Importantly, it is specifically the endothelial cells that have imported PDAC EVs in WT tumors that have a decrease in ICAM-1 surface expression compared with endothelial cells within the same tumor that have not imported EVs." (PMID 40814996, 2025). "Furthermore, CAFs enhance circulating tumor cells’ (CTCs) survival and proliferation by producing pro-survival factors such as regulated upon activation, normal T cell expressed and secreted (RANTES), and intercellular adhesion molecule 1 (ICAM1)." (PMID 39940643, 2025). "Similarly, cell adhesion molecules, such as ICAM1 and SELP, also showed distinct expression patterns across the subgroups, implying potential differences in immune cell recruitment and interaction within the tumor microenvironment." (PMID 39711402, 2024). "This discrepancy may arise from a lack of viral receptors on the cell surface, as the mRNA expression of CAR and ICAM-1 used in this study does not necessarily reflect the presence of sufficient functional receptor proteins on the tumor cell surface." (PMID 39457005, 2024). "Notably, tumors of shICAM-1 and shFGG groups grew slower and displayed spontaneous regression on day 6, followed by a quick and significant shrink in tumor volume in next days, indicating the death of tumor cells when ICAM-1 or FGG was absent." (PMID 39168965, 2024). "Notably, we found that USP7 inhibition increased gene expression levels of ICAM‐1 (log2 fold changes = .85, padj = .017), VCAM‐1 (log2 fold changes = .72, padj = 1.9 × 10−4), and ITGB‐2 (log2 fold changes = 1.26, padj = 1.84 × 10−4) in the tumour." (PMID 38602256, 2024). "Moreover, TECs also interacted with T/NK cells via ICAM1/ICAM2-(ITGAL + ITGB2), which might contribute to immune cell infiltration and effective anti-tumor immune response." (PMID 39093451, 2024). "FGG and integrin β2 bind to distinct binding sites in ICAM-1, shedding light on the possibility of exploiting neutralizing antibodies or compounds to specifically obstruct ICAM-1‒FGG interaction without affecting integrin β2‒ICAM-1 binding involved in anti-tumor immune responses." (PMID 39168965, 2024). "Similar to CD47, ICAM1 is expressed on the tumor cells and not the macrophages." (PMID 38339779, 2024). "ICAM-1 interactions with the β2 integrins located on the surface of leukocytes are important for their firm adhesion to the endothelium.Soluble ICAM-1 can bind to LFA-1 and block its sites on effector cells inhibiting antitumor response and promote tumor progression." (PMID 35876981, 2023). "The mutant ICAM1 P404E rescued tumor killing by CTLs to similar extent as full length ICAM1, whereas no rescue could be detected upon transfection with ICAM1 Y474A+Y485 A." (PMID 37732732, 2023). "Furthermore, the expression of ICAM1 or TGFBI has been shown to be upregulated in TNBC and related to tumor aggressiveness and metastasis, and the expression of both genes were increased in TAB182 KD cells and participated in the cell adhesion process in the present study." (PMID 37953246, 2023). "The efficacies of two ICAM1 ADCs have been evaluated in comparison with the first-line chemodrug Gemcitabine in vitro and in vivo, and ICAM1 antibodies coupled with warhead DX-8951 derivative (DXd) or monomethyl auristatin E (MMAE) elicit a potent and consistent tumor attenuation." (PMID 37717087, 2023).
tumor (continued). "Furthermore, age-related senescence of human peritoneal mesothelial cells has been shown to create a more permissive environment for the metastatic colonization of the peritoneum in CRC, enhancing circulating tumor cells’ adhesion, especially via ICAM-1 (intercellular adhesion molecule 1)." (PMID 38275386, 2023). "ICAM-1 is a molecule whose expression is controlled by the cytokines TNF-α and IL-β, which plays an important role in colorectal pathogenesis, participating in mutual interactions between the tumor and extracellular matrix in signal transduction and numerous immune processes." (PMID 37569878, 2023). "Moreover, chemokine (CXC motif) ligand 13 (CXCL13) in tumors and plasma is correlated with the level of ICAM‐1 and ICI efficacy, suggesting that CXCL13 might be involved in the ICAM‐1‐mediated anti‐tumor pathway." (PMID 37097643, 2023). "Moreover, the combination treatment led to a significantly increased expression level of ICAM1 on tumor cells, which was also observed in the palbociclib group, but palbociclib did not induce ICAM1 expression on immune cells." (PMID 36871040, 2023). "ICAM-1 was broadly expressed, including on non-proliferating tumor cells in the proximal region and CSCs in the border region, which increased the repertoire of cells typically expressing this marker, such as endothelial cells, N1 neutrophils, and licensed DCs." (PMID 36672243, 2023). "Indeed, in the GSE51401 dataset, ICAM1 transcription level was negatively correlated with IL-17A level of tumor tissues and with IL17RC in TECs but not in NECs." (PMID 37605139, 2023). "Interestingly, the absence of ICAM-1 on tumor cells had a stronger negative impact of tumor killing compared to PD-L1 overexpression." (PMID 37732732, 2023). "Notably, the presence of ICAM-1 on E0771 did not alter tumor growth or the leukocyte composition in the tumor microenvironment." (PMID 35911772, 2022). "However, in the ICAM-1 targeted CARTs, the KD of LFA binding ICAM-1 is at micromolar (KD=20μM) to generate the most effective antitumor effects with reduced toxicity in preclinical tumor model." (PMID 36325345, 2022). "However, we need to keep in mind the potential negative impact of having ICAM-1 overexpressed in tumor cells." (PMID 35681548, 2022). "In all tumor models, the gene expression profiles of TANs from SM16-treated tumors revealed a significant decrease in arginase levels and a significant increase in tumor necrosis factor alpha (TNF-α) and intercellular adhesion molecule 1 (ICAM1) levels compared with TANs from SM16-untreated mice." (PMID 36555469, 2022). "Similarly, the elimination of a primary E0771 tumor by a distally implanted homologous tumor also did not require the presence of ICAM-1 on E0771 cells." (PMID 35911772, 2022). "Furthermore, platelet depletion or ICAM‐1 inhibition suppresses tumor growth and metastasis after insufficient RFA in an orthotopic tumor mouse model, and vascular permeability decreases in ICAM‐1−/− mouse tumor after insufficient RFA." (PMID 33643788, 2021). "Whether or not volatile anesthetics affect NK cell-mediated tumor cytotoxicity when tumor cells have very limited ICAM-1 expression remains to be determined." (PMID 34660784, 2021). "Within these vessels, tumor endothelial cells (ECs) exhibit an activated or pro-inflammatory state characterized by increased expression of surface adhesion molecules such as VCAM1 and ICAM1, which facilitate the recruitment and attachment of leukocytes to the vessel wall." (PMID 33853689, 2021). "However, the roles of ICAM1 in the development of CTCs, tumor-cluster formation, and metastasis initiation have not been well studied." (PMID 34381029, 2021). "Maurer’s study found that compared with normal tissues adjacent to cancer, the expression of ICAM-1 (intercellular adhesion molecular-1) in CRC tissues was significantly increased and positively correlated with the infiltration of inflammatory cells in the tumor microenvironment." (PMID 34262597, 2021).